STAT5A (signal transducer and activator of transcription 5A)
Diseases named in the same sentence as STAT5A in open-access papers (continued):
Sharing a sentence is not in itself a finding about the gene and the disease.
mastitis (15 papers, 2009 to 2025). Inflammation of breast tissue during lactation or postpartum due to an obstructed duct or infection. "Five of the genes considered the most promising candidates (i.e., BoLA-DRB3, CXCL8, GC, NPFFR2, and STAT5A) overlap with mastitis-associated QTL (CM or SCS)." (PMID 36759924, 2023). "In previous genome-wide association studies (GWAS), a number of candidate genes (TRAPPC9, mTORC1, JAK2 and STAT5A) were observed to be associated with mastitis-related traits such as SCC." (PMID 32944235, 2020). "In contrast, introgressed regions contain STAT5A and CSF3, both associated with mastitis resistance in cattle, the latter being also linked to gastrointestinal nematode resistance." (PMID 41273432, 2025). "In contrast, introgressed regions contained STAT5A and CSF3, both associated with mastitis resistance in cattle, and genes (CX3CR1 and CSF3) and QTLs involved in immune response and parasite resistance." (PMID 41273432, 2025). "The CpG islands in the promoter regions of JAK2 and STAT5A gene were found to be hypomethylated, resulting in increased gene expression in cows with mastitis compared to healthy controls; the opposite was seen with the CD4 gene." (PMID 39045327, 2024). "A few studies noticed a significant association of polymorphism in the STAT5A and STAT5B genes with mastitis resistance phenotypic traits." (PMID 36911690, 2023). "JAK2 and STAT5A & B are the key parts of JAK-STAT signaling, which have been recently studied for their association with mastitis resistance." (PMID 36911690, 2023). "The evaluation of DNA methylation in promoter regions of JAK2 and STAT5A revealed hypo-methylation levels of CpG sites and higher gene expression in cows diagnosed with mastitis as compared to the healthy control, and vice versa in those with CD4." (PMID 35011171, 2021). "The CpG islands in the promoter regions of the JAK2 and the STAT5A revealed hypo-methylation levels and higher gene expression in cows with mastitis compared to the healthy control, and vice versa in those with the CD4 gene." (PMID 35011171, 2021). "Methylation of the STAT5A DNA-binding sequence in the αS1-casein promoter was reported to repress the prolactin induced expression of the αS1-casein during acute mastitis." (PMID 28077797, 2017). "In addition, abnormal DNA methylation at the CpG site in the 1 kb promoter region of JAK2, STAT5A and CD4 genes caused by mastitis can be used as a potential epigenetic marker to estimate mastitis susceptibility in dairy cows." (PMID 37569258, 2023). "The results of the different DNA methylation levels, although non-significant, between the mastitic cows and the healthy controls, suggest that STAT5A could be considered in future epigenetic studies on mastitis resistance in dairy cattle." (PMID 35011171, 2021). "Moreover, in cows diagnosed with mastitis, the methylation of the STAT5A promoter was lowest compared with JAK2 and CD4, about 9–11%, but the expression of STAT5A still changed significantly." (PMID 40214477, 2025). "Findings of the current study inferred that aberrant DNA methylation in the CpG sites at the 1 kb promoter region in JAK2, STAT5A, and CD4 genes due to mastitis in cows can be used as potential epigenetic markers to estimate bovine mastitis susceptibility in dairy cattle." (PMID 35011171, 2021). "Furthermore, it is suggested that the interactive mechanism of SOCS3, STATs, and JAK2, STAT5A, and STAT5B during milk production and mastitis development should be considered in future rodent-knockout research models." (PMID 33202860, 2020).
chronic myeloid leukemia (13 papers, 2012 to 2026). "Nam and colleagues screened a number of indirubicin derivatives, demonstrating that the most potent compound (E804) blocked Stat5a/b phosphorylation at 10-20 μmol/L in K562 human chronic myelogenous leukemia (CML) cells positive for Bcr-Abl, which drives constitutive activation of Stat5a/b." (PMID 27741508, 2017). "STAP1 and STAP2 inhibit apoptosis of leukaemic stem cells in chronic myeloid leukaemia by binding to BCR-ABL fusion oncoprotein and signal transducer and activator of transcription 5a (STAT5a)." (PMID 37462801, 2023). "Attenuation of Stat5a is sufficient to enhance basal oxidative stress in normal CD34+ and chronic myeloid leukemia cells." (PMID 35812340, 2022). "In chronic myeloid leukemia (CML), STAT5A upregulated the expression level of miR-202–5p, which in turn inhibited USP15 expression to reduce Caspase-6 level and thereby lowered the apoptotic rate in CML cells." (PMID 35871161, 2022). "STAT5A/B are upregulated in myeloproliferative neoplasms, acute lymphoblastic leukemia (ALL), chronic myelogenous leukemia (CML), and B-cell and peripheral T-cell leukemia/lymphoma." (PMID 34281163, 2021). "Amongst others, ALL, myeloproliferative neoplasms, AML, chronic myeloid leukemia (CML), B-ALL, and peripheral T cell leukemia/lymphoma (PTCL) show enhanced STAT5A/B signaling." (PMID 31690038, 2019). "Signal transducers and activators of transcription 5A and 5B (STAT5A and STAT5B) are crucial downstream effectors of tyrosine kinase oncogenes (TKO) such as BCR-ABL in chronic myeloid leukemia (CML) and FLT3-ITD in acute myeloid leukemia (AML)." (PMID 31861239, 2019).
lung carcinoma (12 papers, 2014 to 2026). "After multiple-testing correction, 112 SNPs in eight genes (ATR, EGFR, MET, PIK3R1, PIK3R3, PTPN2, STAT3, and STAT5A) remained significantly associated with lung cancer risk with FDR <0.20." (PMID 28400551, 2017). "The relationship between high STAT5a expression and overall survival in breast and lung cancer observed here is supported by the tumor and normal tissue STAT5a expression results." (PMID 37369132, 2023). "Previously, STAT5A partly inhibited the apoptosis induced by miR-1469 in lung cancer cells, A549 and NCI-H1650." (PMID 35769912, 2022). "The regulation of the drug resistance of lung cancer cells by ARL4C was through activating the β-catenin/JAK2/STAT5A signaling pathway." (PMID 33194732, 2020). "Recently it was reported that miRNA-1469 directly targets STAT5a and promotes lung cancer cells apoptosis." (PMID 27586591, 2016). "Using a large panel of lung cancer cell lines, we identified a set of “antioxidant-capacity” biomarkers (ACB), which were tightly repressed, partly by STAT3 and STAT5A/B in sensitive cells, rendering them susceptible to multiple redox-targeting and ferroptosis-inducing drugs." (PMID 36958250, 2023). "Thus, STAT5A may prevent ME induced apoptosis and serve as a drug resistant mechanism of lung cancer A549 cells in response to water extract." (PMID 35769912, 2022). "In our study we assessed the immunoexpression of STAT5A and STAT5B proteins in lung cancer tissue and found it significantly higher than in normal lung tissue." (PMID 25137041, 2014). "Statistical analysis revealed that both STAT5A and STAT5B protein immunoexpression levels were significantly higher in lung cancer samples as compared with normal (macroscopically unchanged, control) lung tissues (P = 0.048 in case of STAT5A and P = 0.034 in case of STAT5B; U Mann-Whitney's test)." (PMID 25137041, 2014).
gastric cancer (11 papers, 2016 to 2025). A primary or metastatic malignant neoplasm involving the stomach. "Further nude mouse experiments showed that STAT5A knockdown effectively inhibits the growth and metastasis of gastric cancer in vivo." (PMID 38879589, 2024). "Helicobacter pylori infection increased the expression level of METTL3 in gastric cancer cells, thereby leading to the upregulation of STAT5A." (PMID 38879589, 2024). "STAT5A-dependent FABP5 expression plays a carcinogenic role in gastric cancer cells by reprogramming intracellular fatty acid metabolism." (PMID 39588377, 2024). "Studies have found that by influencing the FABP5 expression, which further affects the tumorigenesis of gastric cancer cells, STAT5A can contribute to the process of cellular lipid metabolism." (PMID 35517418, 2022). "Since the expression of STAT4 in gastric cancer cells is low or undetectable, we evaluated the correlation of STAT5A and PD-L1 in the further investigation." (PMID 32391259, 2020). "Taken together, these results indicated that 5-FU-induced upregulation of PD-L1 is mediated by miR-940/Cbl-b/STAT5A in gastric cancer cells." (PMID 32391259, 2020). "DC-SIGNR promoted gastric cancer liver metastasis mediated with HNRNPKP2 which expression was regulated by STAT5A." (PMID 28403883, 2017). "We demonstrate that DC-SIGNR facilitates gastric cancer liver metastasis mediated by HNRNPKP2 regulated by STAT5A via the CXCL12/CXCR4 biological axis." (PMID 28403883, 2017). "In addition, both METTL3 and IGF2BP2 are positively correlated with STAT5A in human gastric cancer tissue samples." (PMID 38879589, 2024). "In the present study, our results suggest that 5-FU-induced upregulation of PD-L1 might be mediated by miR-940/Cbl-b/STAT5A axis in gastric cancer cells." (PMID 32391259, 2020). "Our previous study revealed that the miR-940/Cbl-b/STAT5A axis might regulate PD-L1 in gastric cancer cells." (PMID 32391259, 2020). "Additionally, our data suggested that 5-FU upregulated PD-L1 expression through miR-940/Cbl-b/STAT5A axis in gastric cancer cells." (PMID 32391259, 2020). "Given that Cbl-b could directly interact with STAT5A and increase the ubiquitination of STAT5A, we further examined whether the Cbl-b is involved in 5-FU-induced upregulation of STAT5A and PD-L1 in gastric cancer cells." (PMID 32391259, 2020). "In summary, these findings suggest that the interaction between STAT5A and FABP5 is crucial for promoting fatty acid metabolism and tumor development in gastric cancer, highlighting it as a potential therapeutic target." (PMID 40365984, 2025). "In gastric cancer (GC), miR-940 is involved in the regulation of the PD-1 checkpoint pathway via the CBL-b/Stat5a axis, which ultimately promotes cell migration." (PMID 38462628, 2024). "Notably, prior studies have demonstrated that STAT5A promotes tumor invasion and metastasis by upregulatingCD44 —a cancer stem cell (CSC) marker linked to unfavorable prognosis in gastric cancer (GC)." (PMID 41048344, 2025).
ovarian carcinoma (11 papers, 2010 to 2024). A malignant neoplasm originating from the surface ovarian epithelium. "Other studies have found that high STAT5A expression was normally linked with poor ovarian cancer prognosis." (PMID 35517418, 2022). "In this study, the mutation frequency of STAT5A in ovarian cancer was found to be extremely low, mainly missense mutation in the SH2 domain." (PMID 36524006, 2022). "We found that STAT5a was significantly under-expressed in breast, lung, and ovarian cancers, while STAT5a was significantly overexpressed in lymphoid neoplasm diffuse large B-cell lymphoma, glioblastoma, and glioma." (PMID 37369132, 2023). "Using the GEPIA2 analysis platform, we have found that STAT5a was significantly under-expressed in breast, lung, and ovarian cancer compared with normal tissues, consistent with previous reports." (PMID 37369132, 2023). "Nevertheless, little information was available about how STAT5A affected ovarian cancer development and progression." (PMID 36524006, 2022). "The dual role of activated STAT5A in ovarian cancer invasion demonstrated the complexity of STAT5A function." (PMID 36524006, 2022). "Other researchers had suggested that STAT5A activation was related to the regulation of angiogenesis in ovarian cancer, because VEGF secreted by ovarian cancer cells can activate STAT via VEGFR in the cancer cells." (PMID 36524006, 2022). "Mainly, STAT5A affected cell invasion and DNA damage repair, which can be an essential tool to predict ovarian cancer prognosis." (PMID 36524006, 2022). "We explored STAT5A expression and its effects on cell invasion using ovarian cancer cells and a tissue microarray." (PMID 36524006, 2022). "STAT5A-overexpressed ovarian cancer patients can benefit from multiple types of treatment, including chemotherapy, radiotherapy, and immunotherapy because an essential limiting factor in tumor therapeutic efficacy is tumor cells’ ability to repair DNA damage." (PMID 36524006, 2022). "Using the GEPIA2 database, we found that STAT5a mRNA expression has significantly lower expression in breast, lung, and ovarian cancers, whereas STAT5a mRNA has significant overexpression in lymphoid neoplasm diffuse large B-cell lymphoma, glioblastoma, and glioma compared with normal tissue." (PMID 37369132, 2023). "STAT5A expression and ovarian cancer invasion were negatively correlated (R= -0.38)." (PMID 36524006, 2022). "It is speculated that MMP2 may act as a direct or indirect effect molecule of transcription factor STAT5A to promote the invasion and migration of ovarian cancer, which was in line with previous studies on esophageal cancer." (PMID 36524006, 2022). "In addition, we will construct an ovarian cancer xenograft tumor model and introduce STAT5A or JAK2 recombinant protein to verify the inhibition of MMP2 by high expression of STAT5A, thus affecting the invasion and migration ability of ovarian cancer." (PMID 36524006, 2022). "STAT5A and P-STAT5A, biomarkers identified in ovarian cancer, may offer new perspectives for predicting prognosis and assessing therapeutic effects." (PMID 36524006, 2022). "Consistently, the univariate and multivariate Cox regression analyses of OS in paired ovarian cancer and para-cancerous tissues showed that P-STAT5A rather than STAT5A could be an independent risk factor (P=0.032)." (PMID 36524006, 2022). "Since STAT5A expression was negatively correlated with ovarian cancer cell invasion and DNA repair, STAT5A/P-STAT5A activators or inducers may increase ovarian cancer survivorship and allow more of them to benefit from radiotherapy and chemotherapy, molecular targeted drug therapy, or immunotherapy." (PMID 36524006, 2022). "However, STAT5A mutation only occurred in the group with high STAT5A expression, so there should be no mutation in ovarian cancer with relatively low STAT5A expression." (PMID 36524006, 2022).
ovarian carcinoma (continued). "With regard to clinical stages, while STAT5a, STAT5b, and STAT6 were related to a positive OS both in stages I/II and III/IV ovarian cancer patients, STAT1 and STAT4 were correlated to a favorable OS in stages III and IV ovarian cancer patients." (PMID 28536310, 2017). "Although our proteomics screening identified both STAT5A and STAT5B as upregulated proteins in recurrent ovarian cancer, we focused on studying STAT5B in our shRNA screens because it was also markedly upregulated in our chemoresistant cell lines." (PMID 20585448, 2010). "Our results show that high mRNA expression of STAT1, STAT4, STAT5a, STAT5b, and STAT6, are correlated to a better OS of ovarian cancer patients, especially the high level of STAT1 and STAT4 are significantly related to a favorable OS for serous ovarian cancer patients." (PMID 28536310, 2017). "Besides, a negative correlation was found between the expression of STAT5A and invasion of ovarian cancer cells (R= -0.38, p < 0.01), as well as DNA repair function (R= -0.36, p < 0.01)." (PMID 36524006, 2022).
glioblastoma (10 papers, 2019 to 2025). The most malignant astrocytic tumor (WHO grade IV). "On the other hand, STAT5a was significantly over-expressed in lymphoid neoplasm diffuse large B-cell lymphoma, glioblastoma, and lower-grade glioma." (PMID 37369132, 2023). "Garcinol reduced glioblastoma tumor growth in an immunocompromised mouse model by reducing STAT3/STAT5A expression, enhancing the Bax/Bcl-XL apoptotic ratio, and downregulating the Ki-67 proliferation index, in vivo." (PMID 36193062, 2022). "Because iPA may affect Jak2/Stat5 pathways involved in the transcription of RAD51 we next depleted STAT5a/b in glioblastoma cells by RNAi and tested the mRNA levels of RAD51." (PMID 31993371, 2019). "Furthermore, recurrent glioblastoma displayed a general trend of increased STAT5A expression, suggesting a specific role for STAT5A in maintaining the GBM-SC phenotype." (PMID 31783691, 2019).
glioma (8 papers, 2020 to 2024). A benign or malignant brain and spinal cord tumor that arises from glial cells (astrocytes, oligodendrocytes, ependymal cells). "Gene Set Enrichment Analysis (GSEA) was initially performed which revealed enrichment of multiple signaling pathways related to vasculogenesis in glioma samples with high STAT5A expression from TCGA dataset." (PMID 39310105, 2024). "Given this, our findings were novel in that STAT5A was identified as a TF that can regulate LINC01198 in glioma, which could account for the phenomena we described that LINC01198 was shown to be strikingly elevated in glioma relative to matched normal controls." (PMID 32246817, 2020). "Recent studies have shown that STAT5A can promote the transcription of LINC01198, which promotes the proliferation of glioma cells by stabilizing DGCR8." (PMID 34276757, 2021). "STAT1, STAT3, STAT5A, STAT5B, and STAT6 mRNA expression levels were significantly upregulated in glioma (including GBM, astrocytoma, oligodendroglioma, and anaplastic astrocytoma), compared with normal brain tissues or neural stem cells." (PMID 34276757, 2021). "Subsequently, to further explore the regulation of STAT5A on the transcription of LINC01198, glioma cells were stimulated with recombinant human IL-7." (PMID 32246817, 2020). "In addition, differential gene analysis between STAT5A high and low expression groups was conducted using TCGA-Glioma, CGGA693, and CGGA325 datasets containing extensive glioma tissue bulk RNA-sequencing data." (PMID 39310105, 2024). "STAT5A and STAT5B are predominantly located in the cytoplasm of glioma cells." (PMID 34276757, 2021). "The data we presented here demonstrate that STAT5A operates as a novel transcription factor for LINC01198 in glioma, which has never been reported before." (PMID 32246817, 2020).